DKK3 (dickkopf Wnt signaling pathway inhibitor 3)
Diseases named in the same sentence as DKK3 in open-access papers (continued):
Sharing a sentence is not in itself a finding about the gene and the disease.
prostate tumors (9 papers, 2008 to 2025). "The DKK3 gene, which encodes a secreted protein known as DKK3, has been shown to inhibit the growth and metastasis of prostate tumors." (PMID 40600050, 2025). "The DKK3 gene encodes a secreted protein, Dkk-3, that inhibits prostate tumor growth and metastasis." (PMID 29843383, 2018). "Increased ECM1 and DKK3 mRNA expression in prostate tumors was associated with increased relapse-free survival." (PMID 29858602, 2018). "DKK3 protein expression in prostate tumors is generally down-regulated owing to promoter methylation, whereas DKK3 is highly expressed in the surrounding stroma and endothelium." (PMID 35204808, 2022). "Overexpression of DKK3 has been shown to inhibit prostate tumor growth and metastasis by limiting TGFβ/Smad signaling." (PMID 31819067, 2019). "Dkk3 has recently been shown to be down-regulated in human prostate tumor samples, and DKK1 treatment can inhibit prostate tumor cell growth." (PMID 18478098, 2008). "Reduced DKK3 expression may, at least in part, be explained by promotor methylation, which has been detected in various cancers, including over 65% of prostate tumors." (PMID 20976069, 2010). "Analysis of these genes in patient samples from the TGCA dataset using the MethHC database (methhc.mbc.nctu.edu.tw) confirmed significant hypermethylation of the DKK3, PTGS2, SLC16A5, HFE, and CYP27A1 promoters in prostate tumors, compared to normal prostate." (PMID 29843383, 2018).
bladder cancer (8 papers, 2016 to 2023). "Thus, whether CKAP4 and DKK3 associate with bladder carcinoma prognosis need further studies." (PMID 33614703, 2020). "Furthermore, miR425 was shown to promote gastric and bladder cancer progression, migration, and invasion through direct targeting of mRNA coding Dickkopf-related protein 3 (DKK3)." (PMID 37582765, 2023). "In addition, the relationship between the expression of CKAP4 and its ligand DKK3 in bladder cancer tissues and the prognosis is unclear." (PMID 33614703, 2020). "As a result, Dkk-3 protein expression was especially upregulated in human bladder cancer T24 cells." (PMID 27827955, 2016). "In our study, we found that Dkk-3 was exceptionally upregulated in bladder cancer T24 cells." (PMID 27827955, 2016). "Furthermore, we evaluated Dkk-3 protein expression levels in other human bladder cancer cell lines (NKB1 and 253JB-V) and found that specific upregulation of Dkk-3 in T24 cells." (PMID 27827955, 2016). "However, we found that Dkk-3 was exceptionally upregulated in bladder cancer T24 cells." (PMID 27827955, 2016). "Another research showed that DKK3, the ligand of CKAP4, was highly expressed in bladder carcinoma cells." (PMID 33614703, 2020).
neuroblastoma (8 papers, 2012 to 2025). Neuroblastoma (NB) is the most common solid, extracranial childhood tumor. "In neuroblastoma, mir-92b was reported to modulate the expression of the inhibitory protein-coding Dickkopf-3 gene (DKK3)." (PMID 24325785, 2013). "Specifically in neuroblastoma tumors, low DKK3 expression correlated significantly with poor prognosis, however this was not independent of MYCN amplification." (PMID 23226679, 2012). "Preclinical studies to evaluate the effect of Ad-REIC/DKK3 in neuroblastoma are yet to be conducted." (PMID 23226679, 2012). "DKK3 is secreted in neuroblastoma cell lines, and in primary tumors is found to be expressed in the endothelium." (PMID 23226679, 2012). "Consistent with this, overexpression of DKK3 inhibited the proliferation of MYCN amplified neuroblastoma cell lines in vitro." (PMID 23226679, 2012). "In line with higher DKK3 expression in ganglioneuroma and ganglioneuroblastoma, these tumors had lower levels of miR-92a compared with neuroblastoma." (PMID 23226679, 2012). "In a more recent study of 101 neuroblastic tumors including 88 neuroblastoma tumors, both high DKK3 and DKK2 expression correlated with good prognosis." (PMID 23226679, 2012). "In addition there are two recent studies showing that Dkk3 expression is regulated by miRNA-92 in neuroblastoma cell lines." (PMID 25029272, 2014). "We recently identified the miR-17∼92 cluster as an important mediator of MYCN signaling in neuroblastoma with several components of this cluster down regulating expression of target genes such as DKK3 and members of the TGFβ pathway that contribute to the MYCN driven tumor phenotype." (PMID 23308108, 2013). "We and others recently showed that DKK3 and ESR1 as well as several TGFβ pathway components were down regulated as a result of increased levels of miRNAs encoded by the miR-17∼92 cluster in neuroblastoma." (PMID 23308108, 2013). "Alternative strategies more specific to neuroblastoma may involve the direct targeting of the oncogenic miR-17-92 cluster to re-establish DKK3 expression in MYCN amplified neuroblastoma, or the use of agents which directly affect MYCN expression in neuroblastoma cells such as the BET inhibitor, JQ1." (PMID 23226679, 2012). "An initial study of DKK3 and neuroblastic tumors observed that DKK3 expression was a marker of tumor differentiation, where the highest expression was observed in the most differentiated ganglioneuromas, and the lowest expression in the least differentiated neuroblastoma." (PMID 23226679, 2012). "Similar to DKK3, DKK1 is also reported to be secreted in neuroblastoma cell lines, and downregulated indirectly by MYCN." (PMID 23226679, 2012). "Summary of studies which have observed an inverse relationship between DKK3 expression and MYCN expression and/or MYCN amplification in neuroblastoma." (PMID 23226679, 2012). "In neuroblastoma, the expression levels of MYCN and DKK3 are negatively correlated." (PMID 41244073, 2025). "The precise mechanism by which DKK3 suppresses neuroblastoma tumorigenesis is unclear however this does not appear to be through inhibition of the canonical Wnt/β-catenin signaling pathway." (PMID 23226679, 2012). "In neuroblastoma, demethylating agents are unlikely to be of therapeutic use, as low DKK3 expression was not shown to be due to promoter methylation." (PMID 23226679, 2012).
renal carcinoma (8 papers, 2012 to 2022). A carcinoma arising from the epithelium of the renal parenchyma or the renal pelvis. "A small case-control study (210 renal patients vs. 200 controls) reported GA/AA genotype of rs3206824 in DKK3 and GG genotype of rs17037102 in DKK2 were related with decreased risk of renal cancer and cancer deaths, respectively, in Japanese population." (PMID 27457487, 2016). "The methylation levels of six Wnt antagonist genes (sFRP-1, sFRP-2, sFRP-4, sFRP-5, Wif-1, and Dkk-3) were significantly higher in renal cancer compared to normal renal tissues." (PMID 22325146, 2012). "The DKK3 polymorphisms were associated with renal cancer and that the DKK2 rs17037102 polymorphism might be a predictor for survival in patients with renal cancer after radical nephrectomy." (PMID 26537097, 2015).
benign prostatic hyperplasia (7 papers, 2011 to 2023). A non-cancerous nodular enlargement of the prostate gland. "In benign prostatic hyperplasia, Dkk-3 is more highly expressed in the prostate stroma, particularly in myofibroblasts, compared to the epithelium." (PMID 36497305, 2022). "Changes in the expression of Dkk-3 have also been reported in benign prostatic hyperplasia, but less is known about the expression of Dkk-3 in cancer stroma." (PMID 29858602, 2018). "For the accurate selection of representative areas with low and high DKK3 expression in PCa and benign prostate hyperplasia patients (Ctrl), the tissues were stained with DKK3 as well as with anti-pan cytokeratin (PCK) to identify cancer epithelial and normal epithelial in a tissue section." (PMID 36845147, 2023). "Moreover, using NGS, we further investigated the top DEG involving DKK3 expression in our patient cohort with PCa compared to patients with benign prostatic hyperplasia (BPH)." (PMID 36845147, 2023). "In this study, we investigated the possible mechanisms through which Dickkopf-3 (DKK3) produces its possible protective role in PCa using NGS in both the DKK3 overexpression PCa cell line (PC3) model and our patient cohort consisting of nine PCa and five benign prostatic hyperplasia." (PMID 36845147, 2023).
head and neck squamous cell carcinoma (7 papers, 2015 to 2025). A squamous cell carcinoma that arises from any of the following anatomic sites: lip and oral cavity, nasal cavity, paranasal sinuses, pharynx, larynx, and salivary glands. "Cytoplasmic levels of DKK-3 have been reported to increase during the carcinogenic transition of the oral epithelium and to be higher in tissue samples of head and neck squamous cell carcinoma (HNSCC), where they correlate with β-catenin accumulation." (PMID 38201279, 2023). "Among Dickkopf family, DKK3 gene and protein expression have been shown to be increased in higher grades of OSCC tumors and head and neck squamous cell carcinoma cells and the cellular localization of protein has been changed, as well." (PMID 33346226, 2020).
non-small cell lung carcinoma (7 papers, 2011 to 2023). A group of at least three distinct histological types of lung cancer, including non-small cell squamous cell carcinoma, adenocarcinoma, and large cell carcinoma. "The authors show that DKK-3 enhances apoptosis and retards growth either alone or synergistically with cisplatin in resistant non-small cell lung cancer (NSCLC) cells." (PMID 38201279, 2023). "Its expression is commonly suppressed through hypermethylation of CpG islands in the DKK-3 locus in human cancer cells, including basal breast cancer, non-small cell lung cancer, gastric cancers and colon cancers." (PMID 38201279, 2023). "In this context, downregulation of DKK3 gene expression by DNA promoter methylation in non-small cell lung cancer has been reported to increase resistance to docetaxel." (PMID 29843383, 2018). "In non-small cell lung cancer (NSCLC), overexpressed miR-582-3p maintains stemness features by negatively targeting the regulators of Wnt signalling Axin2, DKK3 and SRP1 for degradation, thereby increasing β-catenin mediated Wnt activity." (PMID 35101137, 2022). "In Non-small cell lung cancer (NSCLC) cells, it was observed that DKK3 overexpression inhibits the growth of NSCLC cells by inducing apoptosis and cell cycle disturbance by transactivating c-myc and cyclin D1 through β-catenin/TCF-4 signaling." (PMID 33670899, 2021). "Increased expression of Wnt ligands (WNT1, 2, 7A) along with decreased expression of Wnt inhibitors (DKK3 and SFRP3) was observed in non-small cell lung cancer." (PMID 21490961, 2011).
Alzheimer disease (6 papers, 2020 to 2025). A progressive, neurodegenerative disease characterized by loss of function and death of nerve cells in several areas of the brain leading to loss of cognitive function such as memory and language. "Dickkopf WNT signaling pathway inhibitor 3 (FC = 0.120, p = 4.74E-02) is significantly down-expressed in the brain tissues of Alzheimer’s disease patients and transgenic mouse models of Alzheimer’s disease." (PMID 40709343, 2025). "We further identify DKK1 and DKK3, involved in both Alzheimer’s disease and cancer progression, as targets of the PrPC-dependent axis." (PMID 35962130, 2022). "On human Alzheimer’s disease tissue, DKK3 is expressed in neurons and in blood vessel walls in the brain." (PMID 32331523, 2020).
myocardial infarction (6 papers, 2020 to 2024). Gross necrosis of the myocardium, as a result of interruption of the blood supply to the area, as in coronary thrombosis. "It has been observed that DKK3 may play a cardioprotective role by preventing ventricular dysfunction and cardiac remodeling after myocardial infarction." (PMID 38803396, 2024). "In addition, DKK3 regulates the JNK p38 signal by negatively regulating apoptosis signals to prevent myocardial infarct-induced cardiac remodeling." (PMID 38678874, 2024). "Furthermore, another study demonstrated that DKK3 protected against the development of myocardial infarction (MI)-induced cardiac remodeling via inhibiting the ASK1/JNK/p38 MPAK signaling pathway." (PMID 35658977, 2022). "Moreover, it has been found that DKK3 ameliorates inflammation via inactivation of ASK1/JNK/p38 signaling in myocardial infarction." (PMID 35658977, 2022). "In addition, some other studies reported that Dkk-3 was a cardioprotective regulator and could protect against cardiac dysfunction following myocardial infarction." (PMID 31918729, 2020). "In myocardial infarction conditions, the absence of DKK3 increased the mortality and infarct size, along with an increase in cardiomyocyte apoptosis and inflammation." (PMID 32331523, 2020). "Previous studies have also shown that DKK3 may reduce activation of inflammatory pathways such as JNK1/2 and p38 pathways as observed in myocardial infarction." (PMID 32331523, 2020).
osteoarthritis (6 papers, 2014 to 2021). A noninflammatory degenerative joint disease occurring chiefly in older persons, characterized by degeneration of the articular cartilage, hypertrophy of bone at the margins and changes in the synovial membrane. "Several of the significantly upregulated genes are associated with risk of lumbar disc degeneration and osteoarthritis assayed in humans or animal models, including Aspn, Dkk-3, and Mmp3." (PMID 31652254, 2019). "Several of these SNVs, rs3771501 (TGFA), rs3993110 (TEAD1/DKK3), rs72979233 (CHRDL2), and rs7967762 (PFKM/WNT10B), are associated with multiple osteoarthritis joint sites." (PMID 34450027, 2021). "Dkk3 expression has been upregulated in osteoarthritis, suggesting its role in the pathogenesis of the diseases." (PMID 27472059, 2016). "A comparison of gene expression profiles between normal and osteoarthritic cartilage demonstrated consistently upregulated Dkk3 levels in osteoarthritis, suggesting its involvement in disease progression." (PMID 27472059, 2016). "Addressing the question of whether Dkk3 has a pro- or anti-inflammatory effect in this situation, it was recently shown that Dkk3 inhibits matrix degradation by inflammatory cytokines in osteoarthritis, thus protecting the cartilage." (PMID 27472059, 2016). "We also confirmed the expression of ANPEP, dickkopf WNT signaling pathway inhibitor 3 (DKK3) and osteoglycin (OGN) by multiple reaction monitoring (MRM) analysis of osteoarthritis synovial fluid samples." (PMID 24533825, 2014). "Inhibitors of WNT (DKK3 and FRZB), and antagonists of BMP/TGFβ (CD109, CHRDL2, DCN FMOD, INHBA and THBS1) signalling were decreased or absent in the aged inner region, consistent with the reported upregulation of these pathways in IDD and its closely related condition osteoarthritis." (PMID 33382035, 2020). "Dickkopf-3 (Dkk3) is a non-canonical member of theDkk family of Wnt antagonists and its upregulation has been reported inmicroarray analysis of cartilage from mouse models of osteoarthritis (OA)." (PMID 26687825, 2016).
pancreatic ductal adenocarcinoma (6 papers, 2015 to 2023). An infiltrating adenocarcinoma that arises from the epithelial cells of the pancreas. "A DKK3-blocking monoclonal antibody has been developed and tested in pancreatic ductal adenocarcinoma, a highly fibrogenic cancer." (PMID 37526081, 2023). "On the other hand, DKK3 has also been reported to stimulate tumor-promoting cancer-associated fibroblasts and suppression of DKK3 has been shown to inhibit tumor growth in pancreatic ductal adenocarcinoma." (PMID 35796776, 2023). "In contrast, DKK-3 expression is upregulated in some cancers, such as squamous cell carcinoma of the head and neck and pancreatic ductal adenocarcinoma, and is correlated with poorer overall survival." (PMID 38201279, 2023). "DKK-3-blocking monoclonal antibodies have also been developed and found to be effective against pancreatic ductal adenocarcinoma progression." (PMID 38201279, 2023). "DKK-3 expression has been found to be high in squamous cell carcinomas of the head and neck and esophagus, and pancreatic ductal adenocarcinoma, and to promote cancer cell proliferation and migration." (PMID 38201279, 2023). "Supporting our results, the oncogenic function of DKK3 has been reported in DKK3-expressing cancers, including pancreatic ductal adenocarcinoma (PDAC), esophageal squamous cell carcinoma (ESCC), and esophageal adenocarcinomas (EAC)." (PMID 36376957, 2022). "For this study, pancreatic ductal carcinoma cell lines Bxpc‐3 were transfected with a DKK3 expression construct." (PMID 26395974, 2015).
adenoma (5 papers, 2013 to 2022). A neoplasm arising from the epithelium. "Differential gene expression analysis of the scRNA-seq data from the adenoma cells showed substantially fewer transcripts encoding the Wnt antagonists Axin2, Dkk2, Dkk3, Wif1, Notum, and Nkd1 in the LApcL mice than in the LApc mice." (PMID 34788095, 2021). "Immunohistochemical analysis showed that DKK3, present predominantly in the cytoplasm of cells, was abundantly expressed in normal ovarian epithelial cells and benign adenoma." (PMID 35205672, 2022). "In this study, we found that DKK3 was significantly downregulated in invasive epithelial ovarian carcinoma compared to that in normal tissue, adenoma, and borderline tumors." (PMID 35205672, 2022). "In the present study, DKK3 consistently displayed increased methylation (log2 fold change = 2.9) in adenomas from Apcmin/+ mice compared with normal tissue." (PMID 26101583, 2015). "For DKK3, 95% (38/40) of the APC mutated samples showed DKK3 methylation whereas only 78% (32/41) showed DKK3 methylation in the APC wild type adenomas (p = 0.026)." (PMID 24350795, 2013). "Combining both adenoma types, a positive trend between APC mutation and both WIF-1 and DKK3 methylation was observed (p < 0.05)." (PMID 24350795, 2013). "To investigate the relation between methylation of SFRP2, WIF-1, DKK3 and SOX17 and the anatomical location of the adenoma, we divided all the adenomas into left- and right-sided adenomas." (PMID 24350795, 2013). "Methylation of SFRP2, WIF-1, DKK3 and SOX17 was significantly higher in carcinomas as well as both types of adenomas compared to normal colorectal mucosa." (PMID 24350795, 2013). "WIF-1 and DKK3 showed a significantly lower level of methylation in nonpolypoid compared to polypoid adenomas (p < 0.01)." (PMID 24350795, 2013). "We found higher levels of methylation for WIF-1 and DKK3 in polypoid adenomas compared to nonpolypoid adenomas." (PMID 24350795, 2013). "The present study focussed on promoter methylation of four known Wnt-pathway antagonists (SFRP2, WIF-1, DKK3 and SOX17), in polypoid and nonpolypoid adenomas, and its possible association with other molecular events that can play a role in Wnt-pathway activation." (PMID 24350795, 2013). "For APC methylation as well as for chromosome 5q loss, no relation was found with the promoter methylation results for SFRP2, WIF-1, DKK3 and SOX17 when combining both adenomas types or in nonpolypoid adenomas or polypoid adenomas, separately." (PMID 24350795, 2013). "Interestingly, DKK3 and WIF-1 methylation frequencies were significantly higher in polypoid adenomas (DKK3; 97% (38/39), WIF-1; 87% (34/39)) compared to nonpolypoid adenomas (DKK3; 76% (32/42), WIF-1; 57% (24/42); p = 0.005 and p = 0.003, respectively)." (PMID 24350795, 2013).